MC4R (melanocortin 4 receptor)
Diseases named in the same sentence as MC4R in open-access papers (continued):
Sharing a sentence is not in itself a finding about the gene and the disease.
Obesity (continued). "Evidence from our previous study suggested that two SNPs (rs17782313 near the melanocortin-4 receptor (MC4R) gene and rs6265 near the brain-derived neurotrophic factor (BDNF) gene) were significantly associated with BMI and obesity, but the molecular mechanisms are not understood." (PMID 28396685, 2017). "The polymorphism of FTO gene rs17817449 and GNB3 gene rs5443 (C825T) may be a genetic determinant of obesity in Saudi population whereas impact of MC4R Asn274Ser change could not be detected." (PMID 29937877, 2017). "Therefore, it is plausible that certain effects of the cardiomyopathy in Mc4r−/− mice are due directly to insulin resistance and/or negative metabolic effects of obesity." (PMID 28829041, 2017). "Thus, the observed increase in myocardial oxygen consumption in Mc4r−/− mice is specific to the myocardium, independent of obesity, and precedes the development of heart failure." (PMID 28829041, 2017). "In addition, ASIP1 overexpression working at central MC4R in transgenic zebrafish model results in enhanced feeding, feed efficiency, weight and linear growth but not in obesity, in a similar way to the AgRP1 transgenic zebrafish." (PMID 28694769, 2017). "The polymorphism of FTO gene rs17817449 and GNB3 gene rs5443 (C825T) may be a genetic determinant of obesity in Saudi population, whereas impact of MC4R Asn274Ser change could not be detected in our sample." (PMID 29937877, 2017). "Although obesity is most commonly polygenic, rare monogenic forms do exist, and the affected genes described thus far include leptin, the leptin receptor, pro‐opiomelanocortin (POMC), single‐minded 1 (SIM1), neurotrophic tyrosine kinase receptor type‐2 (NTRK2), and the melanocortin 4 receptor." (PMID 26788538, 2016). "This lead to the hypothesis; that reduction of hypothalamic MC4R signaling, shortly after initiation of a HFD, may explain the early onset of functional leptin resistance, which contributes, in part, to further manifestations of obesity." (PMID 27551276, 2016). "While it is not known what the response of the MC4R-sensitive neurons in mouse PVN are to obesity, it appears certain that the neurons we have studied represent a different and probably nonoverlapping population of PVN neurons from those expressing postsynaptic melanocortin responses in mice." (PMID 26444289, 2015). "Altered MC4R function does not rule out the effect of other factors that may impact both obesity and RYGB outcomes." (PMID 24705671, 2014). "Vasodilator function was not affected by obesity in MC4R KO rats." (PMID 24400148, 2013). "Indeed, it has been reported that mice with genetic disruption in both Mc3r and Mc4r are heavier than Mc4r−/− mice, indicating a possible non-redundant participation of both melanocortin receptors in obesity and adiposity-related phenotypes." (PMID 21695122, 2011). "Thus, the molecular structure of the TMEM18 protein is very uncommon in terms of other proteins in the human genome and surely very much different compared to other proteins involved in obesity, such as the enzyme FTO and the G protein-coupled melanocortin receptor, MC4R." (PMID 20380707, 2010). "Furthermore, transgenic mice lacking specific proteins expressed in the VMH including leptin receptor, steroidogenic factor 1 (SF-1), melanocortin-4 receptor (MC4R), and brain-derived neurotrophic factor (BDNF), exhibits obesity, hyperphagia, and low locomotor activity similar to AC3−/− mice." (PMID 19750222, 2009). "The authors also showed that mice with a hypomorphic mutation in trkb (resulting in 25% normal levels of expression) closely resembled mice lacking Mc4r in that they developed hyperphagia and obesity, increased body length and excessive weight gain on a high fat diet." (PMID 17448988, 2007).
Obesity (continued). "However, currently, no medications are approved for the treatment of obesity in children younger than 12, with the exception of setmelanotide, a melanocortin-4 receptor agonist approved for select cases of monogenic obesity and Bardet-Biedl syndrome in children aged 2 and older." (PMID 41394113, 2026). "However, the true prevalence of MC4R pathway diseases is unknown because genetic testing is often unavailable or not obtained for individuals with obesity." (PMID 40528426, 2025). "Similarly, no obesity development in mice with MC4R overexpression in PVHMC4R neurons may be due to compensatory changes in upstream POMC neurons." (PMID 37069175, 2023). "Besides SIM1 and MC4R, the haploinsufficiency of proprotein convertase 1 (PCSK1), melanocortin 2 receptor accessory protein 2 (MRAP2) in the brain, iroquois homeobox 3 (IRX3) in fat or uncoupling protein 3 (UCP3) in mitochondria are also responsible for human obesity." (PMID 31124015, 2019). "Also methylation of the MC4R gene body is not related with dog obesity." (PMID 28755272, 2017). "These SNPs were chosen as representative of the obesity status in Western populations (as no comprehensive studies are available yet for the Arabian populations) and because close or within genes whose association to obesity has been well established (e.g., FTO, MC4R)." (PMID 25890290, 2015). "HO patients retain the specific expression of POMC/LEPR/MC4R in the PVN, but there are currently no large-scale clinical studies on the treatment of obesity." (PMID 41601974, 2026). "We aimed to assess the DNA methylation levels in the promoters of MC4R and LPL genes from maternal blood, placenta, and buccal swab samples collected in children born to mothers with and without obesity and Gestational Diabetes Mellitus (GDM)." (PMID 39458497, 2024). "Collectively, these findings demonstrate that the defense against overfeeding-induced weight gain remains intact in obesity and involves mechanisms independent of both FGF21 and MC4R." (PMID 38331907, 2024). "Stimulation of MC4R neurons in the PVH results in pronounced satiation effects and thereby can induce a negative energy balance and confer protection against obesity." (PMID 37443835, 2023). "This latter aspect is clearly illustrated by the unexpected hypomorphic phenotype observed for the WT-hMC4R-KI mice that revealed the lower sensitivity of the human MC4R to α-MSH, which, combined with the lack of β-MSH in mouse, resulted in obesity." (PMID 33434184, 2021). "MC4R haploinsufficiency clearly segregates with higher BMI; however, severe obesity is not fully penetrant even in MC4R LOF carriers, suggesting critical roles for environmental and lifestyle factors in MC4R monogenic obesity." (PMID 29991773, 2018). "To gain insight into the mechanisms responsible for the energy expenditure induction downstream of the MC4R, we tested the ability of DMPP and icilin to reverse obesity in mice lacking β-adrenergic receptors (betaless mice)." (PMID 30353008, 2018). "Among those, genetic loci near MC4R and within BAT2 have effects on type 2 diabetes independent of obesity." (PMID 25093408, 2014). "Although MetS-Z scores have been studied within the general population and in those who have general obesity, to our knowledge, these investigations have not yet been extended to patients with hereditable conditions such as BBS and other MC4R pathway–related diseases of obesity." (PMID 39919037, 2025). "Although MC4R-related obesity is well documented, MC3R-related obesity is not as well studied." (PMID 40001512, 2025). "For example, the difference in expression levels of each of the 13 obesity-related genes between PAAD and PCPG types of cancer was not statistically significant, and the difference in the expression levels of LEP and MC4R in the 21 types of cancer was not significant." (PMID 33299884, 2020).
Obesity (continued). "In any case, the alterations in MC4R expression in DMH seen in DIO-D but not DR animals are consistent with our hypothesis that GABAergic neurons are indeed involved in changes in body weight setpoint in rats, which more closely conform to human diet-related obesity than do mice." (PMID 26444289, 2015).
type 2 diabetes (62 papers, 2007 to 2025). "The recent literature shows that three genes (MC1R, MC2R, and MC5R) increase the risk of major depressive disorder (MDD), and one gene (MC4R) is associated with an increased risk of type 2 diabetes, but its association needs to be researched further." (PMID 41002740, 2025). "Another study showed that the relationship between MC4R 17782313rs polymorphism and type 2 diabetes depends on diet." (PMID 37072742, 2023). "Ile269Asn has been identified as a loss of function MC4R mutation linked to morbid obesity and type 2 diabetes (T2D) in Latinos, by impairing both cAMP production and MC4R internalization by β-arrestin." (PMID 36553534, 2022). "Recent research has demonstrated that Type 2 Diabetes (T2D) risk is influenced by a number of common polymorphisms, including MC4R rs17782313, PPARG rs1801282, and TCF7L2 rs7903146." (PMID 35292917, 2022). "A meta-analysis of 123,373 individuals reported that the rs17782313 polymorphism in MC4R gene has the BMI independent significant association with risk of type 2 diabetes." (PMID 32807123, 2020). "Subsequent analyses have indicated that cardiovascular risk factors, such as insulin resistance, type 2 diabetes, and hypertriglyceridemia, are associated with risk allele C for MC4R rs17782313." (PMID 32758123, 2020). "A Chinese population study revealed that MC4R (rs12970134) was associated with type 2 diabetes after adjusting for BMI." (PMID 32228543, 2020). "In that study, CC-genotype carriers of the MC4R rs17782313 with low adherence to the MedDiet had a higher risk of Type 2 diabetes." (PMID 32019489, 2020). "In another meta-analysis, the association of the MC4R gene with insulin resistance and type 2 diabetes was reported even after adjustment for BMI." (PMID 32807123, 2020). "A study also reported that the allele C of MC4R (rs17782313) was associated with a higher risk of type 2 diabetes mellitus in women." (PMID 32807123, 2020). "Several previous studies reported that the melanocortin-4 receptor (MC4R) (MIM 155541) gene is a candidate as a causal gene for type 2 diabetes." (PMID 32807123, 2020). "In meta-analyses of genetic association studies including over 600,000 people, we now find that V103I MC4R is associated with lower risk of type 2 diabetes (p = 7 × 10−07) and of coronary artery disease (p = 0.003)." (PMID 31002796, 2019). "Conversely, a study in Pima Indians showed an earlier onset of type 2 diabetes in MC4R mutation carriers." (PMID 28472148, 2017). "We found statistically significant gene-diet interactions between the FTO-rs9939609 SNP and the MC4R-rs17782313 SNP, separately, with the MedDiet score in determining type 2 diabetes risk at baseline." (PMID 27598147, 2016). "The population prevalence of these combined functional coding mutations in MC4R was 2.4 %, and in these individuals the rate of increase in body mass index (BMI) and risk of type 2 diabetes (T2D) was more apparent during childhood as compared with adulthood." (PMID 25103139, 2014). "The association of the FTO-rs9939609 and MC4R-rs17782313 polymorphisms with type 2 diabetes depends on diet, and a high adherence to the MedDiet is able to counteract a genetic predisposition to cardiovascular disease." (PMID 25407792, 2014). "In this study, type-2 diabetes mellitus was associated with women carriers of risk allele C for MC4R rs17782313, which remained significant after control for age and BMI." (PMID 23849767, 2013). "This study aimed to investigate the association of FTO rs9939609 and MC4R rs17782313 with anthropometric indexes, BP, and type 2 diabetes mellitus among hypertensive patients." (PMID 23849767, 2013). "The aim of this study was to investigate the association between FTO rs9939609, MC4R rs17782313 with anthropometric indicators, blood pressure, and type-2 diabetes in patients with hypertension." (PMID 23849767, 2013).
type 2 diabetes (continued). "These novel results suggest that the association of the FTO-rs9939609 and the MC4R-rs17782313 polymorphisms with type 2 diabetes depends on diet and that a high adherence to the MedDiet counteracts the genetic predisposition." (PMID 23130628, 2012). "Regarding the MC4R gene, there are fewer studies that have analyzed the association between the rs17782313 polymorphism (or a proxy) with type 2 diabetes than for the FTO gene, and the results are even less conclusive." (PMID 23130628, 2012). "Adherence to a Mediterranean dietary pattern attenuates the association between FTO and MC4R polymorphisms and type 2 diabetes risk; conversely, among individuals with low Mediterranean-diet adherence, carriers of the FTO and MC4R risk alleles exhibit a significantly higher risk of type 2 diabetes." (PMID 41190158, 2025). "A recent study reported that a Mediterranean dietary pattern could influence the relationship between MC4R gene rs17782313 polymorphisms and the risk of type 2 diabetes." (PMID 32807123, 2020). "After adjusting for sex and age, loci near TMEM18 (rs6548238) and FAIM2 (rs7138803), but not SH2B1 (rs7498665), near GNPDA2 (rs10938397), MTCH2 (rs10838738) and near MC4R (rs12970134), were associated with increased risk for type 2 diabetes in obese individuals." (PMID 32228543, 2020). "A recent study reported a strong association with MC4R loci for type 2 diabetes (OR = 1.70)." (PMID 32807123, 2020). "However, two recent large meta-analyses of GWAS identified a significant association between the MC4R locus and type 2 diabetes risk, in European and Asian populations." (PMID 23375129, 2013). "Among hypertensive women, the effect of risk allele C for MC4R rs17782313 on type-2 diabetes mellitus could be mediated by increased visceral adipose tissue." (PMID 23849767, 2013). "Then, outstanding among the dietary factors that could modulate the effect of the FTO rs9939609 and the MC4R rs17782313 polymorphisms on type 2 diabetes, is the Mediterranean diet (MedDiet)." (PMID 23130628, 2012). "The MC4R rs17782313 variant has also been shown to be associated with an increased risk of type 2 diabetes mellitus (T2D) in a meta-analysis that included more than 100,000 individuals; remarkably, this association was independent of BMI." (PMID 32733386, 2020). "Interestingly, MC4R GoF variants were more strongly associated with a reduced risk of type 2 diabetes (OR [95% CI] per kg/m2 genetically lower BMI, 0.86 [0.85–0.87] for the 97-variant polygenic score versus 0.72 [0.62–0.83] for the β-arrestin-biased MC4R GoF variants, Pheterogeneity = 0.01)." (PMID 31002796, 2019). "MC4R is related to regulation of meal consumption and appetite, utilization of energy, thermogenesis, and development of type 2 diabetes mellitus." (PMID 41002740, 2025). "In the PREDIMED study, we focused on two SNPs strongly associated with obesity and type-2 diabetes: the FTO-rs9939609 and the MC4R-rs17782313 polymorphisms." (PMID 27598147, 2016). "Meta-analysis of the association between SNPs near MC4R, GNPDA2 and risk for type 2 diabetes risk in Chinese populations." (PMID 25093408, 2014). "After adjustment for age and sex, two SNPs near the MC4R (rs12970134) and GNPDA2 (rs10938397) genes were found to be significantly associated with type 2 diabetes (P = 4.75×10−4 and 4.54×10−3, respectively)." (PMID 25093408, 2014). "Cardiovascular risk factors as type-2 diabetes mellitus, insulin resistance, and hypertension were associated with the risk allele A for FTO rs9939609 and the risk allele C for MC4R rs17782313, regardless body mass index." (PMID 23849767, 2013). "When adherence to the MedDiet was low, carriers of the variant alleles had higher type 2 diabetes risk (OR=1.21, 95%CI: 1.03-1.40; P=0.019 for FTO-rs9939609 and OR=1.17, 95%CI:1.01-1.36; P=0.035 for MC4R-rs17782313) than wild-type subjects." (PMID 23130628, 2012).
type 2 diabetes (continued). "In conclusion, we described for the first time a statistically significant gene-diet interaction of the FTO rs9939609 and MC4R rs17782313 with adherence to the MedDiet on type 2 diabetes." (PMID 23130628, 2012). "Glycemic control in patients with MC4R-d and Type 2 diabetes improved post-BS." (PMID 35095762, 2021). "We did not observe any significant associations of the three type 2 diabetes-associated SNPs (rs12970134 near MC4R, rs10938397 near GNPDA2, and rs2260000 within BAT2) with these quantitative glycemic traits (all P values>0.05)." (PMID 25093408, 2014). "Finally, we performed meta-analysis that combined previous studies and present findings to provide more precise estimates for the effect of MC4R and GNPDA2 on the risk for type 2 diabetes." (PMID 25093408, 2014). "We identified five additional studies which examined the associations of rs12970134 or its proxy SNP rs17782313 near MC4R with type 2 diabetes and two additional studies examining the associations of rs10938397 near GNPDA2 with type 2 diabetes, all in populations of Han Chinese." (PMID 25093408, 2014). "The multivariate analysis taking into account age and BMI showed that the allele C for MC4R was associated with higher risk of type 2 diabetes mellitus in women (RR = 1.5 95%CI: 1.1 – 2.2, P = 0.03), but not among men (RR = 0.9 95%CI: 0.6 – 1.7, P = 0.9)." (PMID 23849767, 2013). "We did not observe statistically significant differences in genotype frequencies of the FTO rs9939609 or the MC4R rs17782313 polymorphisms between subjects with type 2 diabetes and non-diabetic subjects." (PMID 23130628, 2012). "We found a relevant interaction between adherence to the MedDiet and these polymorphisms in determining type 2 diabetes, which was significant both for the FTO (P-interaction=0.039) and for the MC4R (P-interaction=0.009) as well as for their aggregate score (P-interaction=0.006) (Model 1)." (PMID 23130628, 2012). "Likewise, MC4R knockout mice exhibited increased adiposity and hyperinsulinemia and sometimes, depending on diet, developed type 2 diabetes." (PMID 23130628, 2012). "However, when adherence to the MedDiet was high, the higher risk of type 2 diabetes in subjects carrying variant alleles at both the FTO and the MC4R loci, were completely blunted (OR: 0.86; P=0.266)." (PMID 23130628, 2012). "In the present study, we identified that rs12970134 was associated with type 2 diabetes regardless of BMI and WC adjustment and had a similar effect size in Asians and Caucasians, suggesting a trans-ethnic replication of the effect of MC4R on type 2 diabetes." (PMID 25093408, 2014). "Other genes that were assigned to lead SNPs are involved in regulating satiety and energy homeostasis (MC4R;), adiposity (LYPLAL1;), and metabolic diseases such as type 2 diabetes (KLF14;)." (PMID 38664839, 2024). "Considering that dysregulation in DNA, methylation has been suggested as one relevant epigenetic mechanism in type 2 diabetes and that both the FTO and the MC4R genes are regulated by methylation, the MedDiet might modulate the effect of these genes through epigenetic mechanisms." (PMID 23130628, 2012).